TMPRSS6 (transmembrane serine protease 6)
Diseases named in the same sentence as TMPRSS6 in open-access papers (continued):
Sharing a sentence is not in itself a finding about the gene and the disease.
iron deficiency (continued). "The highest number of SNPs were identified in the TMPRSS6 gene region (n = 23), where the majority were associated with IRIDA, iron deficiency or indicators of low iron status." (PMID 32609760, 2020). "Eleven SNPs had alleles that were clearly associated with low iron, iron deficiency anaemia and/or IRIDA (SNPs in TMPRSS6 (rs855791, rs2235321, rs2235324, rs4820268, rs2413450, rs228916, rs228918 and rs228921) and TF (rs3811647, rs1799899 and rs8177253)." (PMID 32609760, 2020). "This study will determine the interaction between the TMPRSS6 rs855791 variant and nongenetic factors that contribute to the risk of iron deficiency among female medical students in Yogyakarta, Indonesia." (PMID 41159619, 2025). "This study aims to investigate the association of the TMPRSS6 rs855791 variant and nongenetic factors with iron deficiency among female medical students in Yogyakarta, Indonesia." (PMID 41159619, 2025). "Because of the severe iron deficiency in Tmprss6−/− mice fed an ICD, no iron-deprivation studies were conducted in these animals." (PMID 37690687, 2023). "Therapeutic hepcidin mimetics (e.g., rusfertide) and hepcidin agonists (e.g., TMPRSS6 inhibitor and mini−hepcidin PR73 and mHS17) aim to reverse iron deficiency by targeting hepcidin−ferroportin axis, increase iron influx, mobilize tissue iron, and consequently normalize hematological parameters." (PMID 38328786, 2023). "The effects of the HFE mutations H63D and C282Y and of the TMPRSS6 A736V variant were further studied in two cohorts of CeD patients with and without persistent iron deficiency anemia after diagnosis and after being on a gluten free diet for one year." (PMID 32349426, 2020). "The missense variant A736V (TMPRSS6 rs855791) is the most reported SNP associated with iron deficiency and has a MAF of ~50% across all non-African populations, but in Africa it only reaches 10% (7% in the MRCG Keneba Biobank population)." (PMID 32609760, 2020). "Studies have shown a common TMPRSS6 gene variant to be prevalent in 45% of the individuals without iron deficiency and clinically relevant inflammatory conditions and 36.5–41.7% in a group of non-pregnant women." (PMID 32564308, 2020). "Previous mutation on TMPRSS6 has been shown to result in the Matriptase-2 protein lacking activity, which is essential for adequate iron uptake to prevent iron deficiency and to suppress hepcidin expression." (PMID 31010126, 2019). "Tmprss6 mRNA did not significantly change in iron deficiency anemia, highlighting the importance of posttranscriptional regulation of TMPRSS6." (PMID 26845567, 2016). "It was noteworthy that TMPRSS6-/- fetuses and newborns had lower iron content, mean corpuscular erythrocyte volume (MCV), and hemoglobin (Hb), indicating microcytic anemia secondary to iron deficiency in mutant mice." (PMID 25805669, 2015). "In conclusion, in CHD patients the A736V TMPRSS6 genotype influences hepcidin levels, and in the absence of acute inflammation and severe iron deficiency, also erythropoiesis and anemia management." (PMID 23433094, 2013). "After excluding all known causes responsible for iron deficiency anaemia we searched for mutations in SLC11A2 and TMPRSS6 that could explain the severe anaemia in these children." (PMID 22509377, 2012). "Furthermore, IRIDA syndrome was suspected, based on unresponsive iron deficiency, but sequencing analysis of TMPRSS6 did not detect any pathogenic variants." (PMID 40428346, 2025). "Therefore, our study aims to analyze the association of the TMPRSS6 rs855791 variant and nongenetic factors with iron deficiency in apparently healthy female medical students." (PMID 41159619, 2025). "Although we observed a TMPRSS6 increase in DFO-treated hepatoma cells between 24 h and 48 h, HCV infection minimised TMPRSS6 expression altogether, indicating that HCV could overturn the positive impact exerted by iron deficiency on TMPRSS6." (PMID 34571900, 2021).
iron deficiency (continued). "Loss-of-function mutations in the negative regulator of hepcidin transcription, the transmembrane serine protease TMPRSS6 (also called matriptase 2), in mice or humans cause a disease “iron-refractory iron deficiency anemia” (IRIDA) where hepcidin is excessive despite severe iron deficiency." (PMID 34204327, 2021). "In order to test whether iron deficiency plays a role in the transdifferentiation of adipocytes in the absence of Tfr1, we used both Tmprss6 knockout and maternal low‐iron‐diet fed mice, both of which had extremely low iron levels in iBAT." (PMID 32596110, 2020). "Moreover, mice lacking transmembrane serine protease 6 (Tmprss6) develop iron deficiency in both inguinal white adipose tissue (iWAT) and iBAT, and have impaired cold‐induced beige adipocyte formation and brown fat thermogenesis." (PMID 32596110, 2020). "However, a minor fraction of patients with iron-deficiency anemia do not respond to oral iron administration, and this iron-refractory iron deficiency anemia can be caused by mutations in the TMPRSS6 gene." (PMID 29073189, 2017). "Interestingly, in iron-refractory iron deficiency anemia patients, as well as in Tmprss6-mutated mice, this downregulation of hepcidin by ERFE is not functional, and hepcidin transcription does not respond to administration of EPO." (PMID 29073189, 2017). "A GWAS concluded that identifying mutations in the TMPRSS6 gene has broad applications in understanding clinical disorders of iron metabolism, and polymorphisms in TMPRSS6 gene may contribute to iron deficiency anemia (IDA) in individuals even in absence of other predisposing factors for IDA." (PMID 32564308, 2020). "Our data indicate that liver iron stores were not altered by TMPRSS6 siRNA treatment but splenic iron stores increased, consistent with this therapy redistributing iron stores rather than inducing systemic iron depletion, a feature that could protect patients from symptomatic iron deficiency." (PMID 36928379, 2023). "In contrast to the effect of iron deficiency, EPO treatment did not result in increased cleavage of HFE2, despite an increase in TMPRSS6 protein content." (PMID 26845567, 2016). "Iron deficiency anemia is often a multifactorial disorder, and the complex malformative/functional digestive issues of this child may be contributing factors; a hypothesis of IRIDA Syndrome was not confirmed by sequencing analysis of TMPRSS6." (PMID 40428346, 2025).
iron deficiency anemia (59 papers, 2011 to 2025). "A thorough literature search was conducted across databases, including Embase, Google Scholar, and PubMed, focusing on studies investigating TMPRSS6 gene polymorphisms and anemia." (PMID 40081160, 2025). "Studies have shown that individuals with IRIDA are more likely to carry specific TMPRSS6 variants, which disrupt iron regulation and lead to persistent anemia." (PMID 40081160, 2025). "This meta-analysis, which consisted of 2082 cases and 2684 controls, aimed to establish a correlation between anemia and TMPRSS6 gene polymorphisms with a specific SNP." (PMID 40081160, 2025). "This comprehensive meta-analysis examined the association between the TMPRSS6 gene polymorphism (rs855791) and anemia, incorporating data from 13 studies comprising over 4700 participants." (PMID 40081160, 2025). "In the PheWAS analyses, we observed the well-known association of functional variants in iron metabolism genes (the hemochromatosis HFE variant, rs1800562, and the TMPRSS6 variant, rs855791) with disorders of iron and mineral metabolism and anemias." (PMID 38594418, 2024). "One of the intriguing aspects of iron metabolism regulation in Tmprss6-deficient mice is the fact that these mice fail to downregulate hepcidin in the presence of anemia." (PMID 33800732, 2021). "As far as it is known, this is the first study to analyze the associations between a TMPRSS6 polymorphism and anemia in the pediatric population with CD." (PMID 34444942, 2021). "TMPRSS6−/− mice with MT-2 deficiency suffered from microcyter hypochrom anemia accompanied by alopecia, hair follicular dystrophy, and hyperkeratosis." (PMID 31659405, 2020). "Two different pathogenic types of anemia have been examined from the aspects of iron status parameters and the SNPs of three genes (TMPRSS6 A736V, HFE C282Y, and HFE H63D)." (PMID 30984307, 2019). "In contrast, several mutations in the MT-2 gene TMPRSS6 have been reported to cause an inherited form of anemia in humans, referred to as iron refractory iron deficieny anemia (IRIDA)." (PMID 29883401, 2018). "In very rare cases, genetic mutations of iron homeostasis proteins such as DMT1 or TMPRSS6 (Transmembrane Protease, Serine 6), the latter encoding for matriptase-2, can result in inadequate iron absorption and development of anemia." (PMID 27557596, 2016). "Seven years ago it was discovered that this anemia can be caused by mutations in the TMPRSS6 gene which result in inappropriately high expression of hepcidin, the key iron-regulatory hormone." (PMID 26845567, 2016). "Additionally, this study did not differentiate between IDA and iron refractory-iron deficiency anemia (IRIDA), a specific subtype of anemia that is more likely to be influenced by genetic factors such as TMPRSS6 polymorphisms." (PMID 40081160, 2025). "These non-genetic factors are often more prevalent and could overshadow the genetic contributions, making it difficult to detect a direct correlation between TMPRSS6 polymorphisms and anemia." (PMID 40081160, 2025). "Genotype–phenotype studies of a large European cohort of IRIDA patients across multiple unrelated families have proposed that missense mutations affecting the TMPRSS6 mutation through a compound heterozygous phenomenon typically present with less severe anemia and milder hypoferremia." (PMID 36254154, 2022). "The aim of this study was to investigate the association between the rs855791 TMPRSS6 polymorphism, anemia and iron status in children with CD at diagnosis and after treatment with GFD, and to explore the potential link between rs855791 and persistent IDA in this population." (PMID 34444942, 2021). "Gender-related difference in transferrin levels and transferrin saturation associated with TMPRSS6 rs855791 variants in patients with ESRD-related anemia is potentially clinical relevant, but the pathophysiological mechanism should be examined in extensive studies." (PMID 30984307, 2019).
iron deficiency anemia (continued). "This iron sensing machinery appears to be altered by the TMPRSS6 gene mutations in humans, global ablation of Tmprss6 gene (Tmprss6−/−) or a deletion of the Mt2 catalytic domain (mask) in mice, because they all result in an inappropriately high hepcidin and iron-deficiency anemia." (PMID 37690687, 2023). "Further research is needed to understand how variations in the TMPRSS6 gene are connected to anemia." (PMID 40081160, 2025). "Use of antisense oligonucleotides or small interfering RNAs that target TMPRSS6 has been shown to improve anaemia and iron overload in mice and other preclinical models of β-thalassaemia." (PMID 29261151, 2017). "Data from mouse models suggest that deletion of the TMPRSS6 gene improves anaemia and reduces ineffective erythropoiesis, splenomegaly, and iron loading." (PMID 29261151, 2017). "Both models have the same degree of anemia, low transferrin saturation and low liver iron content (LIC), a phenotype quite similar to that of the iron deficient Tmprss6-/-." (PMID 24847265, 2014). "The A736V TMPRSS6 genotype influences hepcidin levels, erythropoiesis, and anemia management in CHD patients." (PMID 23433094, 2013). "This study provides important insights into the lack of association between anemia and variations in the TMPRSS6 gene." (PMID 40081160, 2025). "Previously, we reported about 70% of under two children have iron-lowering allele in TMPRSS6 which contribute to anemia, however, we did not assess this genotype in the current study, which is limitation of this study." (PMID 40561117, 2025). "To further examine whether Hif2α activation can effectively alleviate hepcidin‐activated anemia, we crossed Tmprss6−/− mice with intestine‐specific Hif2α overexpression mice (Hif2αLSL/+) to generate Tmprss6−/−; Hif2αLSL/+ mice." (PMID 38243847, 2024). "Nevertheless, the potential association between TMPRSS6 polymorphisms and anemia in children with CD has not been addressed to date." (PMID 34444942, 2021). "Our findings could contribute to the further investigation of mechanisms involved in the pathophysiology and important gender-related involvement of the TMPRSS6 and HFE polymorphisms on anemia in ESRD patients." (PMID 30984307, 2019). "Understanding the mechanism and the role of inflammation on TMPRSS6 regulation may ultimately lead to new therapeutic strategies to treat diseases where hepcidin levels are deregulated such as β-thalassemia and anemia of chronic disease." (PMID 24376517, 2013). "Therefore, our findings strongly suggest no potential link between the TMPRSS6 rs855791 gene polymorphism and anemia." (PMID 40081160, 2025). "In addition, it has been reported that EPO administration does not improve anemia in patients with TMPRSS6 mutations." (PMID 26845567, 2016). "Studies targeting Tmprss6 in Hbbth3/+ and Hfe knockout mice by injecting silencing RNA and anti-sense oligonucleotides have successfully suppressed Tmprss6 mRNA expression, leading to elevated hepcidin levels, improved iron overload in Hfe knockout and anemia and β-thalassemic mice." (PMID 24966834, 2014). "In the hypothesis that increased hepcidin is involved in the deregulation of iron metabolism and the anemia of CHD, the aim of this study were to evaluate whether the TMPRSS6 A736V polymorphism influences hepcidin levels and erythropoiesis parameters in CHD patients." (PMID 23433094, 2013). "Additionally, our results highlight the important gender-related involvement of the TMPRSS6 and HFE polymorphisms on anemia in ESRD patients and could help further research to investigate whether primary disorder itself modifies patient's response to anemia." (PMID 30984307, 2019). "Moreover, duodenal Hif2α overexpression fully rescues phenotypes of Tmprss6 knockout mice, and Hif2α knockout in the gut significantly delays the recovery from 5‐fluorouracil‐induced anemia, which can not be rescued by FG‐4592 treatment." (PMID 38243847, 2024).
iron deficiency anemia (continued). "Similarly, FG‐4592‐fed Tmprss6‐LKO mice presented significant improvement in anemia‐ and iron‐related parameters without the change of hepatic Hamp levels compared to vehicle‐treated‐Tmprss6‐LKO mice." (PMID 38243847, 2024). "Evaluation of the effect of TMPRSS6 genotype on clinical outcomes in prospective studies in CHD may be useful to predict the outcomes of hepcidin manipulation, and to guide treatment personalization by optimizing anemia management." (PMID 23433094, 2013). "All affected subjects presented with microcytic anemia, but the severity of the anemia was highly variable (Hb range 5.5–12.6 g/dL, MCV range 55–81 fl) and was independent of the TMPRSS6 genotype." (PMID 35893046, 2022). "First, we performed an earlier study using a higher dose of Tmprss6-ASO in PV mice, demonstrating even more robust iron restriction resulting in anemia and increased splenomegaly (data not shown)." (PMID 34890402, 2021).
iron-refractory iron deficiency anemia (25 papers, 2011 to 2026). "Iron refractory iron deficiency anemia (MIM #206200) is a rare recessive genetic disorder due to mutations in the TMPRSS6 gene that lead to a defect in matriptase 2, a protein involved in hepcidin regulation." (PMID 36986429, 2023). "Two of these modifier genes are HFE (H= high FE = Fe, iron homestasis regulator) related with type 1 hemochromatosis and TMPRSS6 (transmembrane serine protease 6) coding for the matriptase 2 and causative of iron refractory iron deficiency anemia (IRIDA)." (PMID 32349426, 2020). "Findings of severe IDA in masked mice have led to further investigations on the TMPRSS6 mutations in humans with iron refractory iron deficiency anemia (IRIDA)." (PMID 31010126, 2019). "Genetic inactivation of the TMPRSS6 gene leads to unrestricted hepcidin production in spite of low body iron stores, which underlies the pathogenesis of iron-refractory iron deficiency anemia (IRIDA)." (PMID 27445804, 2016). "TMPRSS6 is a hepatocyte transmembrane serine protease whose mutations result in iron-refractory iron deficiency anemia." (PMID 26845567, 2016). "Iron-refractory iron deficiency anemia develops due to mutations in TMPRSS6, which is the gene encoding matriptase-2." (PMID 25805669, 2015). "For example, a form of iron refractory iron deficiency anaemia (IRIDA) can be caused by mutations in the gene encoding matriptase-2 [transmembrane protease, serine 6 (TMPRSS6)], a negative regulator of hepcidin." (PMID 26182354, 2015). "Mutations in TMPRSS6 in humans led to iron-refractory iron deficiency anemia (IRIDA) that is unresponsive to oral iron treatment and only partially responsive to parental iron therapy." (PMID 24966834, 2014). "In humans, mutations in TMPRSS6 lead to a genetic disorder characterized by an iron refractory iron deficiency anemia (IRIDA) that is unresponsive to oral iron treatment but partially responsive to parenteral iron therapy." (PMID 24376517, 2013). "Inactivating mutations in TMPRSS6 cause iron-refractory iron deficiency anemia (IRIDA) due to inappropriately high hepcidin levels." (PMID 23917168, 2013). "Iron-refractory iron deficiency anemia (IRIDA) is a rare hereditary disorder caused by pathogenic variants in the TMPRSS6 gene, encoding matriptase-2, a key regulator of hepatic hepcidin synthesis." (PMID 41595494, 2026). "Mutations in the TMPRSS6 gene, another upstream regulator of hepcidin, have been implicated in iron-refractory iron deficiency anemia through linkage studies, although these results are based on a few extended pedigrees and may have limited relevance at the population level." (PMID 21483845, 2011). "The most potent Erfe inhibitor is the liver transmembrane serine protease TMPRSS6 (transmembrane serine protease 6) or matriptase-2 TMPRSS6, which is mutated in patients with iron-refractory iron deficiency anemia (IRIDA)." (PMID 36079046, 2022). "Recently, a new form of hereditary anemia called iron refractory iron deficiency anemia (IRIDA), due to mutations in the TMPRSS6 gene, has been described." (PMID 33193643, 2020). "Iron-refractory iron deficiency anaemia (IRIDA), an iron metabolism disorder, is associated with mutations in the TMPRSS6 gene." (PMID 30135444, 2018).